GDAP1 (ganglioside induced differentiation associated protein 1)
Diseases named in the same sentence as GDAP1 in open-access papers (continued):
Sharing a sentence is not in itself a finding about the gene and the disease.
Vocal cord paralysis (4 papers, 2017 to 2025). A loss of the ability to move the vocal folds. "Further studies for the identification of novel mutations in the GDAP1 associated with vocal cord paralysis and respiratory affection in different ethnic groups are highly recommended." (PMID 37966693, 2023). "Other significant clinical clues in demyelinating CMT subtypes included vocal cord paralysis in GDAP1, ophtalmoparesis and tongue fasciculations in FGD4, severe sensory ataxia in PRX, respiratory involvement in MTMR2 and SBF2, similar to previous reports." (PMID 39776111, 2025).
endometriosis (3 papers, 2023 to 2025). The growth of functional endometrial tissue in anatomic sites outside the uterine body. "Finally, endometriosis-associated mQTLs associated with expression of GDAP1, SRP14, and HOXB9 are in moderate LD (r2 > 0.6) with SNPs significantly associated with endometriosis and with eQTLs for these genes in the recent endometriosis meta-analysis." (PMID 37587191, 2023). "Expression of several of these genes (LINC00339, CDC42, GDAP1, FGD6, SRP14) has been associated with risk of endometriosis previously." (PMID 37587191, 2023). "Expression of four of the genes (EEFSEC, GDAP1, ADK, and SKAP1) was also significantly associated with endometriosis risk when SMR analyses were conducted using the eQTL and GWAS summary statistics." (PMID 37587191, 2023). "The clustering analysis, which reveals pain-related genes (SRP14/BMF, GDAP1, MLLT10, BSN, and NGF), further solidifies the genetic basis for the chronic and often debilitating pain experienced by patients with endometriosis." (PMID 41516028, 2025).
alcohol dependence (2 papers, 2024 to 2025). Physical and psychological dependence on alcohol. "Taken together, results indicate that Gdap1 might not only be associated with alcohol consumption but might even play a role in alcohol dependence." (PMID 40251787, 2025). "In human cohorts, GDAP1 methylation differed between individuals with alcohol dependence and healthy subjects, and even correlated with the degree of dependence." (PMID 40251787, 2025). "Differences in the expression of Gdap1 indicate an important role of this gene in alcohol dependency." (PMID 40251787, 2025). "Studies with human patients collectively indicate that the Gdap1 gene plays a role in alcohol dependence." (PMID 40251787, 2025). "Another explanation of the common mechanism between GDAP1 and alcohol dependence could be neuroinflammation." (PMID 40251787, 2025). "Using the AUDIT and the GSI score as an indicator for alcohol dependency, they found a negative association between these scores and GDAP1 methylation as well as a negative association between GDAP1 methylation and the years of alcohol dependency." (PMID 40251787, 2025). "Despite the important role of GDAP1 in cellular physiology, little is known about how the gene is regulated at the transcriptional and epigenetic levels, though previous studies have suggested that methylation of the GDAP1 5′-flanking region could be a prognostic marker for alcohol dependency." (PMID 39328838, 2024).
Charcot-Marie Tooth neuropathy (2 papers, 2015 to 2022). "GDAP1 and MFN2 are outer mitochondrial membrane (OMM) proteins and both are related to Charcot-Marie Tooth neuropathy." (PMID 35177962, 2022).
polyneuropathy (2 papers, 2020 to 2024). A disease or disorder affecting more than one nerve. "Charcot-Marie-Tooth (CMT) disease 4A (MIM#214400) is an autosomal-recessive polyneuropathy caused by mutations in ganglioside-induced differentiation-associated protein 1 (GDAP1)." (PMID 39070058, 2024). "In this model, dominant GDAP1 mutations, which cause a hereditary polyneuropathy, would adopt a super-active conformation resulting in toxic hyper-fission activity while recessive GDAP1 mutations with reduced fission activity would adopt the inactive state." (PMID 32230997, 2020).
acoustic nerve disorders (1 paper, 2021). "Peculiar was the phenotype of the two patients with the GDAP1 variant, who presented with proximal/asymmetric lower limb weakness, clinical signs of first motoneuron involvement, and optic and acoustic nerve disorders." (PMID 34942918, 2021).
bipolar disorder (1 paper, 2023). A disorder of the brain that causes unusual shifts in mood, energy, activity levels and the ability to carry out day-to-day tasks. "The importance of TLE6 to brain-related disease is supported through its association with bipolar disorder, and mutations in GDAP1 cause inherited peripheral neuropathies." (PMID 37149835, 2023).
breast carcinoma (1 paper, 2025). "For TGFB2-dependent biomarkers, elevated TGFB2 mRNA expression is a prognostic biomarker associated with breast cancer patients that is correlated with improved OS outcomes at high expression levels of GDAP1, TBL1XR1, RNFT1, HACL1, SLC27A2, NLE1, and TXNDC16." (PMID 41373732, 2025). "In cases dependent on TGFB2, increased mRNA expression of TGFB2 alongside higher levels of GDAP1, TBL1XR1, RNFT1, HACL1, SLC27A2, NLE1, or TXNDC16 was correlated with improved OS among breast cancer patients, of which four genes were upregulated in tumor tissues (SLC27A2, TXNDC16, TBL1XR1, GDAP1)." (PMID 41373732, 2025). "Our studies indicated that the prognostic impact was TGFB2 mRNA-dependent using both the Cox proportional hazards model and the Kaplan–Meier analysis, suggesting that breast cancer patients with high levels of both TGFB2 and GDAP1 expression displayed significantly improved OS outcomes." (PMID 41373732, 2025).
dependence (1 paper, 2025). "Future studies should investigate if a controlled manipulation of hippocampal Gdap1 expression, for example, by using viral constructs, leads to altered alcohol consumption and behavior associated with dependence." (PMID 40251787, 2025).
Dysphonia (1 paper, 2023). Difficulty in speaking due to a physical disorder of the mouth, tongue, throat, or vocal cords. "Patients with GDAP1 mutations and autosomal recessive neuropathy present with dysphonia and require interventions such as surgery, braces, physical therapy, and exercise." (PMID 37966693, 2023).
mulibrey nanism (1 paper, 2024). A prenatal onset growth disorder with multiorgan manifestations. "Genes mediating mitochondrial and peroxisomal fission, and pexophagy show no tissue specificity, except for the neuronal fission factor GDAP1, and cerebral enrichment of the E3 ubiquitin ligase TRIM37, which corresponds to the primary neurological phenotype in mulibrey nanism." (PMID 38365851, 2024).
optic atrophy (1 paper, 2021). A disorder characterized by loss of optic nerve fibers. "Ganglioside Induced Differentiation Associated Protein 1 (GDAP1), a glutathione S-transferase enzyme that seems to be a regulator of mitochondrial fission, although with still unclear mechanism of action, is associated with a form of CMT occasionally presenting also optic atrophy." (PMID 33806088, 2021).
pancreatic cancer (1 paper, 2025). "A high level of GDAP1 expression was correlated with improved survival in pancreatic cancer patients (HR: 0.71 [95% CI: 0.57–0.90]; p = 0.004)." (PMID 41373732, 2025).
type 2 diabetes (1 paper, 2023). "Genetic variants in or near the CDKAL1, KLF9, GP2, ALDH2, and ITIH4 genes are associated with obesity and genetic variants in or near the GDAP1, PTF1A, SIX3, ALDH2, and PAX4 genes are specifically associated with type 2 diabetes in East Asians." (PMID 37749090, 2023).
uterine disorder (1 paper, 2024). A non-neoplastic or neoplastic disorder that affects the uterine corpus or the cervix. "The uterine disorders cluster (two) was significantly associated with six loci, WNT4, GREB1, BSN, SYNE1, GDAP1, and ASTN2." (PMID 39315247, 2024).
peripheral neuropathy (15 papers, 2011 to 2026). A disorder affecting the peripheral nervous system. "Intriguingly, different pathogenic GDAP1 variants appear to cause peripheral neuropathy via different mechanisms." (PMID 33810506, 2021). "Neuron-derived cells are a suitable model to study GDAP1-associated effects due to the involvement of GDAP1 in the pathogenesis of peripheral neuropathies." (PMID 33477664, 2021). "GDAP1 is one of the genes associated with peripheral neuropathies caused by missense mutations." (PMID 35509130, 2022). "GDAP1 was one of the first regulators of mitochondrial dynamics linked to peripheral neuropathy, and mutations in this gene are the most common cause of autosomal recessive axonal CMT (CMT4A), although intermediate or demyelinating neurophysiologic findings are also well-described." (PMID 33810506, 2021). "Thus, there are multiple types of cellular dysfunction that likely contribute to peripheral neuropathy in patients with pathogenic variants in GDAP1." (PMID 33810506, 2021). "Human JPH1 is a modifier of the GDAP1 mutations causing Charcot–Marie–Tooth peripheral neuropathy." (PMID 29208631, 2018). "Loss of MFF has been linked to mitochondrial encephalomyopathy and early-onset Leigh-like encephalopathy, optic atrophy, and peripheral neuropathy; and mutations in GDAP1 have been shown to cause Charcot-Marie-Tooth disease, the most common inherited peripheral neuropathy." (PMID 28538669, 2017). "Ablation of the mitochondrial network regulator Gdap1 in SCs leads to an age-related hypomyelinating peripheral neuropathy, recapitulating aspects of the Charcot–Marie–Tooth disease seen in patients with mutated Gdap146." (PMID 34078899, 2021). "Intriguingly, pathogenic variants in many of the peripheral neuropathy proteins discussed here lead to hyperfused mitochondrial networks (e.g., SLC25A46, DRP1, MFF, GDAP1, MYH14)." (PMID 33810506, 2021). "Treatments of peripheral neuropathies might consequently involve genetic approaches to introduce wild type MFNs and GDAP1, as shown recently in a MFN2 transgenic mouse model, or pharmacological approaches to target these proteins." (PMID 34295920, 2021). "Mt-ER contacts, which are impacted by variants in several peripheral neuropathy proteins (e.g., MFN2, GDAP1, ATL3), are important for mediating mitochondrial function, but are also important for mitochondria fission, motility, and likely by extension quality control." (PMID 33810506, 2021). "Characterization of this model revealed that the absence of GDAP1 induces a peripheral neuropathy with loss of motor neurons and abnormal neuromuscular junctions." (PMID 25860513, 2015). "In order to gain insight into the cellular pathogenesis of GDAP1 defects and disease pathophysiology we have generated and characterized a knockout mouse model of recessive forms (CMT4A/2K) of GDAP1-related peripheral neuropathy." (PMID 25860513, 2015). "Thus, the observed motor behavior deficits suggested that lack of GDAP1 leads to a peripheral neuropathy phenotype." (PMID 25860513, 2015).
cancer (4 papers, 2015 to 2025). A tumor composed of atypical neoplastic, often pleomorphic cells that invade other tissues. "Recently, GDAP1 has also been implicated in the survival of patients with certain cancers." (PMID 39328838, 2024). "Moreover, accumulating evidence indicates that GDAP1 expression may be associated with the development of certain cancers and could be a factor influencing patient outcomes." (PMID 39328838, 2024). "However, the importance of GDAP1 in cancers, including AML, has not yet been revealed." (PMID 36708053, 2023).
mitochondrial disease (2 papers, 2011 to 2024). "Finally, the GDAP1 LSDB, which is part of the mitodyn.org portal of databases of genes incriminated in disorders involving mitochondrial dynamics and bioenergetics, should yield new insights into mitochondrial diseases." (PMID 22200116, 2011).
neurodegenerative disease (2 papers, 2020 to 2021). A disorder of the central nervous system characterized by gradual and progressive loss of neural tissue and neurologic function. "Together with earlier data, our results provide important clues toward the structure and function of GDAP1 on the outer mitochondrial membrane and its involvement in neurodegenerative disease." (PMID 33585569, 2020).
tumor (2 papers, 2023 to 2025). "Four of these genes were significantly upregulated in tumor tissues (p < 0.0001 for all comparisons): SLC27A2, TXNDC16, TBL1XR1, and GDAP1." (PMID 41373732, 2025). "While overexpression of GDAP1 induced increased MMP, LDH silencing can activate OXPHOS in several tumor cell lines." (PMID 37393339, 2023).
genetic disorder (1 paper, 2014). "CMT2 is a highly heterogeneous genetic disorder but 4 genes are the most frequently involved : the GJB1 (connexin-32), MPZ (P0 or myelin protein-zero), MFN2 (mitofusin 2) and GDAP1 (ganglioside-induced differenciation-associated protein 1)." (PMID 24804794, 2014).
neuromuscular disease (1 paper, 2017). "Mutations in a similar human gene (GDAP1) cause Charcot-Marie-Tooth type 4A, and this plus the result with mouse Gdap1l1 suggests that human GDAP1L1 is a candidate for neuromuscular disease." (PMID 28190221, 2017).
peripheral nervous system disease (1 paper, 2021). "We also observed that proteins enriched in GO term of peripheral nervous system disease, including MAP4, MTM1, MYO5A and GDAP1, were significantly increased in T2DM‐MCI patients." (PMID 34528736, 2021).
GDAP1 also shares sentences with these, for which no sentence is quoted: Sensory neuropathy (4 papers); centronuclear myopathy (2); Parkinson disease (2); acute myeloid leukemia (1); alcohol addiction (1); autosomal dominant optic atrophy (1); central core myopathy (1); Charcot-Marie-Tooth disease type (1); Charcot-Marie-Tooth type 2 (1); congenital myopathies (1); cystic fibrosis (1); Encephalopathy (1); Friedreich ataxia (1); hearing loss (1); hereditary motor and sensory neuropathy (1); hereditary spastic paraplegia 7 (1); limb-girdle muscular dystrophy (1); maple syrup urine disease (1); motor neuron disease (1); myofibrillar myopathies (1); neurodevelopmental disorder (1); neurological disorders (1); sarcoglycanopathies (1); sensory ataxia (1); spinal muscular atrophy (1); Wilson disease (1).